CCL4 (C-C motif chemokine ligand 4)
Diseases named in the same sentence as CCL4 in open-access papers (continued):
Sharing a sentence is not in itself a finding about the gene and the disease.
periodontal disease (1 paper, 2021). "TNFα (p = 0.0038), MCP1 (CCL2) (p = 0.0493), IL-1β (P = 0.0043), and IL-8 (p = 0.0035) were increased in OSCC compared to control only while MIP1β (CCL4) (p < 0.0365) was increased in OSCC patients compared to periodontal disease patients." (PMID 35048057, 2021).
peripheral nerve injury (1 paper, 2023). Injury to a peripheral nerve. "It has also been reported that cc-chemokine ligand 4 (CCL4) is involved in the induction of neuropathic pain after peripheral nerve injury, confirming our results that CCL4 is one of the hub genes." (PMID 37123369, 2023).
pituitary tumor (1 paper, 2023). A benign or malignant neoplasm affecting the pituitary gland. "Chemokines, such as CXCL8 (or interleukin (IL)-8), CCL2, CCL3, and CCL4, are secreted by pituitary tumors and non-tumor cells, such as macrophages, lymphocytes, or fibroblasts, and modulate the microenvironment composition." (PMID 37958702, 2023).
Pleural effusion (1 paper, 2025). The presence of an excessive amount of fluid in the pleural cavity. "Comparing the percentage of CD8 subpopulations in pleural effusion between HP and LCP patients, CXCR3lo TEM was significantly increased, whereas CCL4+ TEM was notably decreased." (PMID 40959273, 2025).
pneumococcal meningitis (1 paper, 2013). An acute purulent infection of the meninges and subarachnoid space caused by Streptococcus pneumoniae, most prevalent in children and adults over the age of 60. "In vitro, antibodies against CCL2, CCL3, and CCL4 inhibited monocyte chemotactic properties of CSF from patients with pneumococcal meningitis." (PMID 23997430, 2013). "The intracisternal inoculation of recombinant CCL3 and CCL4 induced BBB disruption, CSF leukocytosis, and cerebral edema in a rabbit model of pneumococcal meningitis." (PMID 23997430, 2013).
polyp (1 paper, 2024). A usually exophytic mass attached to the underlying tissue by a broad base or a thin stalk. "Therefore, an increase in CCL4 in normal mucosa and a decrease in polyp would reduce the probability, and an increase in CCL4 in both tissues would increase the malignancy risk." (PMID 38338661, 2024). "We found that an increase in CCL4 expression in a polyp reduces the baseline likelihood of malignancy." (PMID 38338661, 2024). "In patients stratified based on polyp type, CCL4 expression differed significantly between lesion and normal mucosa in V while CXCL2 expression differed between lesion and normal mucosa in T and T-V." (PMID 38338661, 2024). "Likewise, CCL4 expression in normal mucosa was significantly higher in singular polyp as compared to multiple polyps and extensive carpet-like lesions." (PMID 38338661, 2024). "As indicated by the significant but small negative φ, an upregulation of CCL4 expression in the polyp would lower the likelihood of malignancy associated with polyp’s histological type." (PMID 38338661, 2024). "Unpaired analysis on a larger set of samples confirmed lack of significant differences in CCL4 and CCL19 expression with respect to polyp size, both in lesions and normal mucosa." (PMID 38338661, 2024).
pressure ulcers (1 paper, 2021). "For the mild SCI Δ2bp carriers, risk of pressure ulcers was positively associated with circulating levels of IFN-γ, CXCL10, and CCL4 and negatively associated with circulating levels of IL-12p70." (PMID 33956875, 2021). "For the Δ2bp carriers in mild SCI, our data suggested that these individuals were at higher risk of pressure ulcers and were associated with higher circulating levels of IFN-γ, CXCL10, and CCL4 but lower circulating levels of IL-12p70." (PMID 33956875, 2021). "In mild SCI, the risk of pressure ulcers was associated with circulating levels of IFN-γ, IL-12p70, CXCL10, and CCL4, and the associations were influenced by the Δ2bp variant." (PMID 33956875, 2021). "Thus, for the Δ2bp carriers in mild SCI, a higher risk of pressure ulcers was associated with higher circulating levels of IFN-γ, CXCL10, and CCL4 and lower circulating level of IL-12p70." (PMID 33956875, 2021).
primary hypertension (1 paper, 2022). "A study on children with untreated primary hypertension also discovered CCL4/macrophage inflammatory protein‐1‐beta to be significantly elevated when compared to healthy peers." (PMID 36467791, 2022).
prostate tumors (1 paper, 2023). "Strikingly, CCL3 and CCL4 also comprise 2 of the immune genes with reproducibly increased expression in BL compared with WH prostate tumors, a finding replicated in multiple independent array-based studies but conspicuously absent from RNA-Seq–based studies such as TCGA." (PMID 36752203, 2023).
Pruritus (1 paper, 2023). Pruritus is an itch or a sensation that makes a person want to scratch. "It was shown that the expression of genes encoding inflammatory mediators such as CCL4, CCL7, CCL8, CCL20, interleukin-19 (IL-19), IL-20, IL-26, IL-36A, IL-36G, and TNF-α) was unique to psoriatic skin with pruritus." (PMID 37834183, 2023).
pulmonary sarcoidosis (1 paper, 2011). Sarcoidosis affecting the lung parenchyma. "In an effort to clarify discrepancies between these studies, we performed the largest observational study involving BALF CC chemokines (CCL2, CCL3, CCL4, and CCL5) during the pathogenesis of pulmonary sarcoidosis." (PMID 21463523, 2011). "BALF CCL3 and CCL4 levels from pulmonary sarcoidosis patients were not increased compared to controls." (PMID 21463523, 2011). "Furthermore, based on our results as well as those from other investigators we think that CCL3 and CCL4 do not have a substantial role in the pathogenesis of pulmonary sarcoidosis." (PMID 21463523, 2011).
renal cell carcinoma (1 paper, 2014). "Thus, the investigators concluded that the antineoplastic effect of CCL4 was due to the suppression of angiogenesis in renal cell carcinoma." (PMID 25401103, 2014). "Similarly, overexpression of CCL4 was observed in the tissues of renal cell carcinoma." (PMID 25401103, 2014).
somatotropinoma (1 paper, 2019). "NF-PitNETs secreted higher amounts of cytokines/chemokines than somatotropinomas, especially CCL2 (16x more), IL-8 (25x more) and CCL4 (27x more), except for FGF-2 which was found in higher concentrations in somatotropinoma supernatants." (PMID 31703742, 2019). "NF-PitNETs were more often secreting IL-8, CCL2, CCL4, IL-6 and PDGF-AA than somatotropinomas." (PMID 31703742, 2019).
squamous cell tumors (1 paper, 2020). "CCL4 expression in serum was observed to be higher in EAC patients (n = 14) compared to squamous cell tumors (n = 36) in one study, suggesting potential differences in the immune response to these histological cancer subtypes." (PMID 33202734, 2020).
status epilepticus (1 paper, 2013). Status epilepticus is defined as a continuous seizure lasting more than 30 min, or two or more seizures without full recovery of consciousness between any of them. "Moreover, increased Ccl4 mRNA expression has been reported in rat hippocampi and temporal lobe tissue following status epilepticus events triggered by electrical stimulation of the amygdala." (PMID 24282673, 2013).
Streptococcus pneumoniae infection (1 paper, 2012). "γδ TCR deficient mice show decreased neutrophil accumulation in small intestine and lungs triggered by thermal injury or Streptococcus pneumoniae infection, due to the impairment of CCL4/MIP-1β, CXCL1 (keratinocyte derived chemokine, KC), and CXCL2/MIP-2." (PMID 23316161, 2012).
synovitis (1 paper, 2018). Inflammation of a synovial membrane. "The study researchers showed that local CCL4 levels were associated with color Doppler ultrasound activity and RAMRIS synovitis scores." (PMID 29955612, 2018).
synucleinopathy (1 paper, 2024). A neurodegenerative disease that is characterized by the abnormal accumulation of aggregates of alpha-synuclein protein in neurons, nerve fibers or glial cells. "Our interest on CCL4 derives from its ability to attract NKTs among other immune cells, suggesting that in models of synucleinopathy the increased trafficking of some lymphocytic populations to the CNS might be in part mediated by CCL4 and that anti-CD1d immunotherapy might disrupt this process." (PMID 38622654, 2024).
syphilis (1 paper, 2018). A contagious bacterial infection caused by the spirochete Treponema pallidum. "The individual with an initial syphilis at study inclusion had a more pronounced elevation in IL-10, IFNα, CCL4 and IP-10 than the individuals with repeat syphilis." (PMID 30253745, 2018). "Our findings of lower plasma IFNα and CCL4 in later episodes of syphilis is commensurate with immunological and clinical findings from other studies." (PMID 30253745, 2018). "Of the 11 individuals, his baseline syphilis contained the highest or second highest levels of IL-10, IFNα, CCL4 and IP-10 (Participant 11)." (PMID 30253745, 2018). "A diagnosis of syphilis in humans and animal models is typically characterized by elevations in both plasma pro-inflammatory (TNFα, IFNγ, CCL4, IP-10) and anti-inflammatory cytokines (IL-10)." (PMID 30253745, 2018). "The fact that repeat episodes had lower IFNα and CCL4 even after excluding the only individual whose baseline syphilis represented an initial infection suggests that each additional episode of syphilis results in a more attenuated immune response than the previous episode." (PMID 30253745, 2018).
thymoma (1 paper, 2021). A neoplasm arising from the epithelial cells of the thymus. "The overall survival data from GEPIA2 demonstrated that low levels of FAU, RPS17, and RPS 24 were significantly associated with shorter survival, while high CCL4 was significantly associated with shorter survival in thymoma patients." (PMID 34760386, 2021).
thyroid cancer (1 paper, 2021). "Most chemokines were downregulated in thyroid cancer, including CCL3, CCL4, CCL15, CCL21, and CXCL13." (PMID 33414407, 2021).
toxoplasmosis (1 paper, 2021). A parasitic disease contracted by the ingestion or fetal transmission of toxoplasma gondii. "We then asked if neutrophils could be one of the sources of CXCL8, CCL4, CXCL9, and CXCL10 during toxoplasmosis." (PMID 34607465, 2021).
ulcers (1 paper, 2021). "It is suggested that the ulcers might be due to subcutenous injection of CCL4." (PMID 33773560, 2021).
uveitis (1 paper, 2017). An inflammatory process affecting a part of or the entire uvea. "We have determined that several of these genes (e.g., CCL4, Jun, and MMP9) are likely to be important for the pathogenesis of uveitis." (PMID 28505077, 2017).
vasculitis (1 paper, 2021). "Third, via MCODE program we have discovered the protein interaction network between CCL4 and NPY2R, future analysis should more concentrate on underlying up/down regulation between them which might be the mechanism leading to vasculitis moreover vascular deteriorations in BD." (PMID 34975900, 2021).
tumor (552 papers, 2007 to 2026). "These are Ccl4+Cd274+Lcn2+Ptgs2+ immunosuppressive neutrophils implicated in EMT induction in tumor cells." (PMID 40568084, 2025). "Higher levels of CXCL10, IL-9, and CCL4 in the tumor tissues were found to be associated with higher numbers of T cells in direct contact with tumor cells." (PMID 40497965, 2025). "For instance, neutrophils with elevated SiglecF expression are linked to tumor progression, and specific subsets, such as CCL4+ TANs and PD-L1+ TANs, recruit macrophages and suppress T cell cytotoxicity, respectively." (PMID 41322421, 2025). "Among other notable DEGs, PD-L1+ clusters were also defined by high expression of many transcripts encoding for chemokines that have been shown to be released by suppressive tumor-associated neutrophils such as Ccl2, Ccl3, Ccl4, Ccl5, Ccl12, Ccl17, and Cxcl16." (PMID 39392875, 2024). "CCL4 (a CC chemokine) induces the recruitment of tumor-associated macrophages and regulatory T cells that exert pro-tumorigenic effects." (PMID 39011399, 2024). "Within the macrophages, we identified two clusters of tumor-associated macrophages (TAMs; Fcgr2b+, Ccl4+, Trem2+) and one enriched in complement genes (C4b+, Cfp+, C1qb+)." (PMID 38570533, 2024). "In turn, the anti-tumor effects of CCL4 are associated with recruitment of CD103+ DCs, responsible for priming and activating CD8+ T cells recruited into TME." (PMID 38338661, 2024). "These two populations expressed genes Cxcl3, Ccl3, Ccl4, Atp6v1c1, Atp6v0d2, which have been associated with a tumor promoting phenotype." (PMID 38265267, 2024). "Prior studies have suggested a pro-tumorigenic role for CCL4+ and PD-L1 in immune cells, particularly tumor-associated neutrophils." (PMID 39457014, 2024). "β2AR signaling can also polarize macrophages from M1 to M2 type, thereby enhancing anti-inflammatory cytokines like IL-10, IL-4 & IL-13, and decreasing pro-inflammatory cytokines like INFγ, TNFα, IL1β, CCL2, CCL3 and CCL4 to cause tumor progression." (PMID 37006295, 2023). "The IFIT1+, SPP1+ and CCL4+ TANs were identified as pro-tumour, were associated with a poorer prognosis and had the highest levels of PD-L1 expression." (PMID 37534829, 2023). "In this study, we demonstrated that SCD1 in tumor cells suppresses antitumor CD8+ T cells through decreased numbers of DCs in tumors via the reduced level of DC-recruiting CCL4 caused by activation of the β-catenin pathway." (PMID 35793868, 2022). "The MOF shell then dissociated and released Mn2+ as a cofactor to self-activate DNAzyme for β-catenin suppression, which in turn caused a persistent CCL4 excretion to promote the infiltration of DCs into the tumor." (PMID 36157510, 2022). "At the same time, there was an upregulation of genes coding chemokines, e.g., Ccl3, Ccl4 previously linked to the attraction of T cells to the tumor bed36." (PMID 35760796, 2022). "CCL4 reportedly promotes tumor development and progression by recruiting tumor-associated macrophages and regulatory T cells." (PMID 35884919, 2022). "Second, we examined gene expression levels for a selection of chemokines associated with T cell recruitment to the tumor, namely CCL4, CCL5, CXCL9, CXCL10." (PMID 33806316, 2021). "In the tumor-bearing mice, IL-6, CCL4 and VEGF were increased by RT in the tumor-associated fat pad." (PMID 31752313, 2019). "CCL4 and IFNγ, inflammatory markers associated with tumor progression, were also reduced with PFD treatment." (PMID 31492002, 2019). "We suggested A/G genotype CCL4 rs10491121 polymorphism recruit different T lymphocyte subsets increasing anti-tumor immunity, which benefits the inhibition of tumor growth." (PMID 28404909, 2017). "Compared to the WT genotype, patients with A/G heterozygotes of CCL4 rs10491121 A/G polymorphism showed a significantly lower risk (p=0.046) for being at an advanced tumor size (> T2)." (PMID 28404909, 2017).
tumor (continued). "Intratumoral injection of CCL4 or CCL5 increased tumor-infiltrating Tregs, and deficiency of CCR5 led to their profound decrease, emphasizing the importance of CCR5 in the control of antitumor immune responses." (PMID 24591756, 2014). "In addition, the association of CXCL10 and CCL4 levels with the densities of all T cell subtypes increased when the tumor cell nests were specifically analyzed." (PMID 40497965, 2025). "Compared to Mo detected in normal brains, Mo detected in PDOXs showed higher expression levels of genes associated with pro-tumorigenic TAMs (e.g., Cxcl13, Ctsd, Ccl4, Apoe) as well as Mg mimicry (e.g., Spp1, Trem2, Cst7, Tyrobp), further confirming an active crosstalk with tumor cells." (PMID 38566128, 2024). "We next evaluated whether CCL3 and CCL4 induction was a widespread phenomenon or whether it was only associated to the 4T1 tumor." (PMID 35064009, 2022). "This indicates the high potential of CCL4 to induce infiltration of tumor-associated macrophages which may be related to tumor progression or metastases associated with high levels of CCL4, which was found in our study." (PMID 35407400, 2022). "We performed gene set enrichment analysis (GSEA) and gene set variant analysis (GSVA) with gene sets coexpressed with CCL4, and observed that gene sets positively related to CCL4 were enriched in tumor proliferation and immune-related pathways while metabolic activities in the negatively one." (PMID 34900664, 2021). "Both CCL3 and CCL4 cause the recruitment of MDSC into the tumor niche via CCR5." (PMID 33076281, 2020). "In addition, CCL2, CCL3, and CCL4 were reported as chemokines associated with worse prognosis and faster tumor progression." (PMID 33238581, 2020). "The results suggest that CCL4 promotes VEGF-C dependent tumor-associated lymphangiogenesis in vivo." (PMID 29599774, 2018). "The gene polymorphisms may increase CCL4 levels and reduce antitumor immunity in tumor microenvironment." (PMID 28404909, 2017). "CCL4 (C-C chemokine ligand 4), a macrophage inflammatory protein with a key role in inflammation and immune-regulation, was implicated in carcinogenesis by facilitating instability in the tumor environment." (PMID 28404909, 2017). "Therefore, the mutation of rs10491121 possibly affects γδT cell recruitment by CCL4, thus causing a higher level of γδT cells in Chinese individuals with cancer and consequently reducing cancer susceptibility and improving tumor immunity of Chinese individuals." (PMID 37593100, 2023). "Furthermore, the cell fraction of Tumor-associated macrophage M1 and Tumor-associated macrophage M1 with high expression of CCL4 in the tumor thrombus showed about 5 fold (and 8 fold, respectively) more abundance than that in the tumor microenvironment of the primary tumor." (PMID 37244923, 2023). "The overexpression of CCL4 in CC may induce the infiltration of tumor-associated macrophages, especially the distribution of pretumor macrophages, and there was a positive correlation between plasmatic CCL4 and inflammatory mediators, which have been suggested a poor prognosis." (PMID 34124251, 2021). "In this study, we extracted a potential immune-related biomarker CCL4 from high-throughput sequencing profiles that might promote aggressive tumor proliferation and be positively associated with immune infiltration levels and the immunotherapy response in ccRCC." (PMID 34900664, 2021). "The expression of CCL4 may also occur in tumor-associated neutrophils (TAN)." (PMID 33076281, 2020). "Intracellular cytokine staining revealed that, compared with healthy lymph nodes, EBL tumor-affected lymph nodes showed increased proportions of CCL4 expressing cells, particularly among CD4+ T cells and B cells." (PMID 42158858, 2026). "It was found to prompt the secretion of the chemokine CCL4 by tumor cells, enhancing the infiltration of cytotoxic CD8+T cells into the HCC microenvironment." (PMID 41800083, 2026).